GZMB (granzyme B)
Diseases named in the same sentence as GZMB in open-access papers (continued):
Sharing a sentence is not in itself a finding about the gene and the disease.
Hepatitis (8 papers, 2015 to 2024). Inflammation of the liver. "Catumaxomab's off-target activity involved T-cell mediated lysis of the granzyme B cell death pathway and the molecular interaction of hepatic sinusoidal macrophages with T-cells induced cytolytic hepatitis." (PMID 27058902, 2016). "Transfection of Sb9 in hepatocytes confers resistance to killing by cytotoxic T cells and hepatotoxicity, suggesting that delivery of Sb9 protein or transgene to liver might be a new strategy for prevention or treatment of GzmB-induced hepatitis." (PMID 38966643, 2024). "However, cytopathic CD335 + NK and granzyme B + /PD-1- NKT cells might be responsible for the hepatitis symptoms in HBV-s-rec mice." (PMID 38129531, 2023). "Patients with hepatitis flare manifest evident activation of CD8+ T cells, and increased frequency of TEMRA subsets and expression levels of perforin and granzyme B may perform crucial functions in breaking down immune tolerance and causing hepatitis flare." (PMID 35493501, 2022). "For example, the predominant TRM cells associated with the pathogenesis of AIH are CD8+CD69+CD103+ TRM cells that highly express PD1, CXCR3 and granzyme B; whereas liver TRM cells of patients with acute hepatitis A are mainly CD8+CD69+CD103- TRM cells that express high levels of HIF-2α." (PMID 36172356, 2022). "Earlier studies had demonstrated how in cases of CD11b-deficient NK cells, following the treatment with or without poly(I:C), that the β2 integrin CD11b attenuate poly(I:C)-induced hepatitis resulted in greater power of cytotoxicity and a greater level of IFN-ɣ and granzyme B released." (PMID 32211442, 2020). "Given the protective role of Sb9 in regulating cell apoptosis, the modulation of homeostasis between Sb9 and GzmB emerges as a potential therapeutic strategy for various conditions, including cancers, HIV, autoimmune disorders, renal transplantation, and hepatitis." (PMID 38966643, 2024). "In patients with checkpoint inhibitor mediated hepatitis, increased frequencies of perforin expressing peripheral CD8+ T cells were detected, additionally increases in granzyme B were measured which was not correlated in our analyses." (PMID 38045689, 2023).
lung adenocarcinoma (8 papers, 2018 to 2025). A carcinoma that arises from the lung and is characterized by the presence of malignant glandular epithelial cells. "Cancers such as Head and Neck Squamous Cell Carcinoma, Renal Clear Cell Carcinoma, and Stomach Adenocarcinoma have higher GZMB expression levels compared to lower-expressing GZMB cancers such as Lung Squamous Cell Carcinoma and Lung Adenocarcinoma." (PMID 40002821, 2025). "In addition, patients with lung adenocarcinoma lack antitumor innate immunity at baseline including tumor-infiltrating NK cells, which are less cytolytic due to low expression of granzyme B and interferon-gamma." (PMID 35565302, 2022). "There has been no prior study regarding the correlation between TMB and expression of GZMB, but a retrospective analysis on lung adenocarcinoma showed that both TMB and RNA expression of GZMB are decreased substantially with age42." (PMID 37553332, 2023).
triple-negative breast carcinoma (8 papers, 2017 to 2025). An invasive breast carcinoma which is negative for expression of estrogen receptor (ER), progesterone receptor (PR), and human epidermal growth factor receptor 2 (HER2). "For example, research analyzing patients with triple-negative breast cancer showed that those with high GZMB expression levels had greater overall survival rates in addition to increased recurrence-free survival." (PMID 40002821, 2025). "In studies related to GZMB, it was observed that in the PD-L1-positive group, Kaplan–Meier analysis revealed better recurrence-free survival (RFS) and OS in triple-negative breast cancer (TNBC) patients with high expression of GZMB (defined as ≥ 1% tumor-infiltrating lymphocytes (TILs) positive)." (PMID 38833021, 2024). "We found that GZMB+ CD8+ T cells from the immune-rich type had a higher expression of CXCL13, which was also reported to be associated with good responses to immunotherapies in triple-negative breast cancer." (PMID 36729271, 2023). "In triple-negative breast cancer (TNBC) tumors, when GZMB levels are high, the levels of tumor-infiltrating lymphocytes are also high." (PMID 40860340, 2025). "In other studies, researchers demonstrated the use of granzyme B-specific (GZP-PET) imaging to monitor changes in effector cell activation in response to treatment with paclitaxel (PTX) and immunological inhibitors in a mouse model of triple-negative breast cancer." (PMID 38338997, 2024).
cutaneous leishmaniasis (7 papers, 2010 to 2025). Leishmaniasis affecting the skin. "Specifically, in cutaneous leishmaniasis caused by L. braziliensis miR-361-3p, a regulator of GZMB and tumor necrosis factor (TNF) was down-regulated and related to treatment failure." (PMID 34178725, 2021). "Good prognosis in patients with cutaneous leishmaniasis, infected with L. major, has been associated with the expression of granzyme B in tissue lesions." (PMID 21072232, 2010). "The level of GZMB is low in healthy skin but is significantly increased in inflammatory and chronic skin diseases, such as cutaneous leishmaniasis, diabetic ulcers, hypertrophic scarring, and autoimmune skin disorders." (PMID 37090158, 2023). "One published work has recently suggested the measurement of granzyme B as a new marker for asymptomatic individuals and those clinically cured of VL and cutaneous leishmaniasis." (PMID 26496365, 2015). "Studies have shown that localized skin inflammation in cutaneous leishmaniasis leads to a chronic systemic IFN-γ signature, with increased expression of cytotoxic markers GZMB, Pore-forming protein 1(PRF1), and GNLY." (PMID 39342024, 2024). "In a recent transcriptomic study of skin samples of cutaneous leishmaniasis patients, delayed or absence of cure was correlated with higher expression of gene sets related to the cytolytic pathway, including mRNAs for granzyme (GZMB), perforin (PRF1), and granulysin (GNLY)." (PMID 34178725, 2021).
liver cancer (7 papers, 2021 to 2025). An epithelial or non-epithelial malignant neoplasm that arises from the liver. "The loss of granzyme B-expressing CD4+ T cells predicted poor survival in liver cancer." (PMID 34631551, 2021). "Based on the ability of EPE to increase the release of Granzyme B and Perforin in NK cell, we co-cultured NK cell with K562 liver cancer cells and assessed the expression of CD107a on the NK cell surface to evaluate NK cell toxicity and activity." (PMID 41357886, 2025). "CD8+ T cells are the main TILs in liver cancer and can release perforin and granzyme B through the Fas/FasL pathway or kill target cells by releasing IFN-γ and TNF." (PMID 34335575, 2021). "While the immune response to ICI therapies differs in HCC compared to many other cancers, granzyme B may still be a potential biomarker for immunotherapy efficacy in liver cancer providing useful information to help improve patient management." (PMID 35936114, 2021).
lupus nephritis (7 papers, 2017 to 2025). Glomerulonephritis in the context of systemic lupus erythematosus. "Furthermore, transcriptomic single cell analysis has revealed the presence of subsets of tissue resident memory CD8+ T cells and cytotoxic CD8+ T cells expressing perforin, granzyme B and granulysin in renal tissue from patients with lupus nephritis." (PMID 39719886, 2025). "Moreover, particularly PTECs showed an elevated expression of the active form of caspase-3 in lupus nephritis—an enzyme involved in the induction of apoptotic cell death—whose proteolytic activation can be induced by GzmB." (PMID 35563816, 2022). "In addition, renal CD8+ T cells expressing GzmB or another granzyme, GzmK, have been identified in lupus nephritis patients." (PMID 35563816, 2022). "The data support the hypothesis that the regulatory function of B-cells via Granzyme B is reduced in active disease and in patients with lupus nephritis." (PMID 31240224, 2019). "SLE-patients had a significant decreased percentage of Granzyme B+ B-cells in particular SLE-patients with active disease and with lupus nephritis." (PMID 31240224, 2019).
metastatic tumor (7 papers, 2017 to 2025). "GZMB + TILs were markers of immune escape from primary tumors and were associated with metastatic tumors." (PMID 37219794, 2023). "Furthermore, the density of PD-1+, ICOS+ and Granzyme B+ TILs, a marker of immune escape/activation, in the primary tumor was associated with that in the metastatic tumor." (PMID 29614981, 2018). "Although it did not apply to all of the markers, some of the activation/suppression marker values (i.e., ICOS and Granzyme B) of the primary tumor were significantly correlated with those of the metastatic tumor." (PMID 29614981, 2018). "Overall, Granzyme B delivered directly to tumor cells or tumor neovasculature appears to be a promising and exciting opportunity in the field of targeted therapy, with significant therapeutic potential in primary and metastatic disease." (PMID 28714916, 2017). "In agreement with our in vitro finding, administration of CFTRi significantly reduced Arg1 expression levels in MoMs, increased CD8+ T cell infiltration and their activation (GzmB+CD8+; CD69+CD8+ T cells) in early metastatic tumors." (PMID 38355776, 2024). "Furthermore, the activation/suppression marker values of the lymphocytes (i.e., such as PD-1, ICOS, Granzyme B and the PD-1/CD8 ratio) in the primary tumor were correlated with values in the metastatic tumor." (PMID 29614981, 2018).
parasitemia (7 papers, 2010 to 2020). "Fast responders usually have an inflammatory phenotype, rapidly initiating T cell responses that promote IFN‐γ production and effectively control parasitemia through CD107a+ and granzyme B+ T cells but may suppress humoral immunity." (PMID 31605396, 2020). "Effector cells from day 8 CPS-primed mice were compared to naïve splenocytes and evaluated for granzyme B and IFN-γ co-expression ex vivo and in response to live parasite infection or peptide restimulation." (PMID 20333242, 2010). "Although the percentage of NK cells in tumor-draining lymph nodes (TdLNs) was not significantly different between the groups, parasitic infection increased the number of granzyme B-secreting NK cells in TdLNs." (PMID 21931708, 2011).
rectal cancer (7 papers, 2019 to 2026). A primary or metastatic malignant neoplasm that affects the rectum. "The LINC02474 oncogene prevents apoptosis and promotes metastasis in CRC by inhibiting GZMB expression, a process that is associated with the poor prognosis of rectal cancer patients (39, –, 42)." (PMID 41358726, 2026). "The effector T-cell phenotype was equally prevalent in the circulation of the healthy individuals and rectal cancer patients but unsurprisingly with much higher cytotoxic activity (granzyme B and perforin expression, correlating with the WB-mtDNA TVN) in the patients." (PMID 34961902, 2022). "A study of 130 rectal cancers with CRT compared to a cohort group of 30 non‐radiated cancers showed a decrease in both CD3+ and CD8+ lymphocyte levels, while the ratio of cytotoxic CD8+/granzyme B+ cells increased." (PMID 39253758, 2024). "Gene expression levels of GZMA, GZMB, PRF1, IFNG and chemokine CXCL10 were compared between responsive versus non-responsive rectal cancer patients." (PMID 35534879, 2022).
urothelial carcinoma (7 papers, 2015 to 2025). A malignant neoplasm derived from the transitional epithelium of the urinary tract (urinary bladder, ureter, urethra, or renal pelvis). "Studies identified GZMB expression in urothelial carcinoma (UC) tissues, revealing statistically significant correlations between its expression levels and tumor grading, and demonstrating that GZMB remodeled the ECM in UC by cleaving desmoglein, thus enhancing tumor invasive capabilities." (PMID 41567188, 2025).
aneurysm (6 papers, 2012 to 2024). Bulging or ballooning in an area of an artery secondary to arterial wall weakening. "Studies in murine models show that GzmB deficiency reduces aneurysm incidence, emphasizing its involvement in aneurysm progression." (PMID 38846935, 2024). "Elevated GzmB levels and the cleavage of fibrillin-1 signify its crucial role in vessel wall destabilization, a hallmark of aneurysm pathology." (PMID 38846935, 2024). "Decorin degradation by GzmB has been shown to contribute to a loss of collagen density in the adventitia of the aorta during abdominal aortic aneurysm, contributing to aneurysm rupture, exsanguination and mortality in mice." (PMID 24205352, 2013). "In arterial walls, inflammatory responses attract immune cells that secrete GzmB, which may contribute to arterial wall damage and susceptibility to aortic dilation and aneurysms." (PMID 38846935, 2024). "During aneurysm progression, GzmB cleaves many extracellular matrix proteins including DCN and fibrillin-1 both of which play pivotal roles in maintaining vessel wall stability." (PMID 29158532, 2017). "The animal study did not, however, show an increase of the final products TNF and GZMB in the aneurysm group." (PMID 25993291, 2015). "Similarly, the use of an extracellular GzmB inhibitor, serpina3n, also protected against aneurysm rupture due to increased adventitial collagen." (PMID 24205352, 2013). "The murine serine protease inhibitor, Serpina3n (SA3N), prevents Granzyme B (GzmB)-mediated DCN degradation and improves collagen remodeling leading to a reduced aneurysm rupture rate and death in a murine model of AAA15." (PMID 29158532, 2017).
dermatitis (6 papers, 2021 to 2025). An inflammatory process affecting the skin. "Plasma GzmB concentrations were significantly higher in AD patients than in healthy controls and positively correlated with pruritus and dermatitis severity." (PMID 37908364, 2023). "The findings further showed that E-cadherin was reduced in the epidermis of both GzmB −/− and WT mice with OXA dermatitis compared with control skin, and the reduction was more pronounced in WT mice compared to GzmB −/− mice." (PMID 37908364, 2023). "Granzyme B expression was positively correlated with severity of clinical skin disease (according to dermatitis score) among both PX-478– and vehicle-treated mice." (PMID 37526979, 2023). "The plasma level of GZMB was elevated in AD patients and positively correlated with the severity of pruritus and dermatitis." (PMID 37330465, 2023). "GZMB levels in plasma might reflect the degree of pruritus and dermatitis in patients with Alzheimer’s disease." (PMID 33542475, 2021). "DCN exhibits both anti-angiogenic and anti-fibrotic properties, and previous studies have shown that genetic deletion or pharmacological inhibition of GzmB can prevent DCN cleavage and increase DCN levels in several skin disorders." (PMID 41310732, 2025).
endometrial cancer (6 papers, 2019 to 2025). Primary or metastatic malignant neoplasm involving the endometrium (mucous membrane that lines the endometrial cavity). "There is evidence that microsatellite unstable endometrial cancer has infiltration of granzyme B + cells, activated cytoxic T-lymphocytes, and PD-L1 + cells, which suggests that endometrial cancer can be treated with immunotherapy to improve prognosis." (PMID 32339157, 2020). "Besides, Granzyme B + cells have increased expression in high microsatellite instability (MSI-H) endometrial cancer, providing a therapeutic target for immunotherapy." (PMID 33324448, 2020).
Granuloma (6 papers, 2019 to 2025). A compact, organized collection of mature mononuclear phagocytes, which may be but is not necessarily accompanied by accessory features such as necrosis. "In NHPs, low burden granulomas were associated with a higher proportion of a T/NK cell cluster expressing granzyme B." (PMID 40162896, 2025). "The central pro-inflammatory environment of granuloma is also linked to increased levels of neutrophils overexpressing granzyme B (grzB), as shown in human and macaque granulomas, a pro-apoptotic enzyme associated with cytotoxic T-cells." (PMID 37492257, 2023). "Taken together, CD4 and CD8 T cells from Mtb/SIV granulomas have a more immune activated (more cytokines and granzyme B production) profile than Mtb/αCD4 and LTBI control groups and this was associated with the loss of control of latent infection." (PMID 32730321, 2020). "While granulomas were less frequent and the parasite load was higher in LST-, there were more CD8+ T cells and an enhanced production of Granzyme B in the supernatants of biopsies from LST- subjects." (PMID 39599571, 2024).
neuroblastoma (6 papers, 2017 to 2025). Neuroblastoma (NB) is the most common solid, extracranial childhood tumor. "Addition of recombinant TGF-β1 to in vitro co-cultures of neuroblastoma tumoroids and primed healthy donor NK cells significantly reduced tumor killing and granzyme B production by NK cells, whereas blockade of TGF-β increased cytotoxicity." (PMID 38181797, 2024). "Unexpectedly, CD56bright NK cells from children with neuroblastoma dramatically upregulated granzyme B expression in response to cytokine with an average of 6-fold and 9-fold increase for IL2 and IL12/15 respectively." (PMID 36276144, 2022). "Here, NK cells recognize anti-GD2 coated neuroblastoma cells and kill them using a suite of cytotoxic molecules including granzyme B and perforin." (PMID 36276144, 2022). "Thus, in marked contrast to IL12/15 failure to induce IFNγ production, NK cells from patients with neuroblastoma robustly upregulated granzyme B in response to cytokine." (PMID 36276144, 2022). "expanded NK cells and isolated NK‐Exos loaded with cytotoxic proteins, including perforin, granzyme A, granzyme B, granulysin and FasL, and found that NK‐Exos triggered cytochrome C release from mitochondria and ER stress in recipient neuroblastoma (NB) cells." (PMID 37830387, 2023). "In neuroblastoma, it was revealed that proteins within NK-cell-derived sEVs, such as perforin, granzyme A, granzyme B, and granulysin functioned in combination to induce cytotoxicity to CHLA255, a neuroblastoma cell line." (PMID 37762393, 2023). "The CD56bright cells in our neuroblastoma patients were characterized by high CD16 expression and high levels of granzyme B and their origin requires further investigation." (PMID 36276144, 2022).
type 1 diabetes (6 papers, 2012 to 2025). "To specifically test the role of granzyme B in beta cell destruction in type 1 diabetes, we have backcrossed granzyme B-deficient mice onto the NOD genetic background." (PMID 22792290, 2012). "Our data indicate that granzyme B is dispensable for beta cell destruction in type 1 diabetes, but is required for efficient early activation of CTL." (PMID 22792290, 2012). "Our data demonstrate that granzyme B is dispensable in the development of type 1 diabetes in NOD mice." (PMID 22792290, 2012). "GzmB increases inflammation in type 1 and type 2 diabetes and impairs insulin secretion from islet cells as part of the mechanism by which it kills pancreatic β cells in the development of type 1 diabetes." (PMID 26375667, 2015). "We generated granzyme B-deficient non-obese diabetic (NOD) mice to test whether granzyme B is an important effector molecule in spontaneous type 1 diabetes." (PMID 22792290, 2012). "For instance, in type 1 diabetes, MAIT cells mediate pancreatic β‐cell damage by secreting IFN‐γ and GZMB." (PMID 41179703, 2025). "On the other hand, a study focusing on the type 1 diabetes NOD mouse model, and assessing granzyme B and IFN-γ production as markers of CD8+ and CD4+ T-cell activation following MERTK inhibition with UNC2025 challenge, found incomplete penetrance." (PMID 37958886, 2023).